CD4 (CD4 molecule)
Diseases named in the same sentence as CD4 in open-access papers (continued):
Sharing a sentence is not in itself a finding about the gene and the disease.
typhoid fever (7 papers, 2011 to 2024). A bacterial infectious disorder contracted by consumption of food or drink contaminated with Salmonella typhi. "Using intracellular staining by flow cytometry, we also showed that lymphocytes from convalescing typhoid patients stimulated for 6 hours with MP contained more CD4+ cells expressing IL-17 compared with patients in the acute stage of typhoid fever." (PMID 24615129, 2014). "Moreover, functional CD4 cells are necessary to combat typhoid fever in healthy adults and transient defects in these cells have previously been associated with opportunistic typhoid fever infection." (PMID 27780232, 2016). "PagC is also well recognized by antibodies and CD4 T cells of human typhoid fever patients." (PMID 23093937, 2012). "On the other hand, CD4 T cells are even more important for immunity to Salmonella at least in the mouse typhoid fever model, and it is unclear why CD4 T cells should respond to surface-associated antigens in a fundamentally different way compared to the much larger number of internal antigens." (PMID 23093937, 2012). "We show that in patients with typhoid fever, prominent IFN-γ responses are seen in both acute and convalescent phases of infection, the majority of which involve CD4 cells." (PMID 24615129, 2014). "Immunization of human volunteers with Salmonella Ty21a, the licensed typhoid fever vaccine, producing HP0231 indicated an antigen-specific CD4+ T cell response and mild protective effect." (PMID 23056345, 2012).
acute leukemia (6 papers, 2011 to 2025). A clonal (malignant) hematopoietic disorder with an acute onset, affecting the bone marrow and the peripheral blood. "According to the analyzed literature, only a few research groups were able to fully evaluate the percentage of Treg cells in the peripheral blood of patients with acute leukemia based on the most appropriate phenotype—CD4+CD25highCD127low/-FoxP3+ T cells." (PMID 30944830, 2019). "Thiosulfate sulfurtransferase shows limited expression and activity in CD4+ and CD8+ lymphocytes and some ALL cell lines, with the TST gene identified as a valuable target for distinguishing acute leukemias." (PMID 39062461, 2024). "We describe a patient with isolated skin involvement who progressed to CD4+/CD56+ and CD123+ acute leukemia." (PMID 36879711, 2023).
acute promyelocytic leukemia (6 papers, 2017 to 2024). An aggressive form of acute myeloid leukemia (AML), characterized by arrest of leukocyte differentiation at the promyelocyte stage, due to a specific chromosomal translocation t(15;17) in myeloid cells. "The HL-60 cell line was established from the peripheral blood of a 36-year-old patient with acute promyelocytic leukemia with aberrant CD4 expression." (PMID 29348865, 2017). "During the analysis of promyelocytic leukaemia zinc finger (PLZF) expression, we noticed that around 40% of CD4+ mature thymocytes expressed a higher level of PLZF than that in innate memory-like CD8 T cells." (PMID 31980555, 2020).
arteriosclerosis (6 papers, 2010 to 2024). A vascular disorder characterized by thickening and hardening of the walls of the arteries. "Graft ECs expressing MHC molecules are a major target of this alloresponse, causing activation of CD4 memory T cells and IFNγ production that is vital for arteriosclerosis." (PMID 26324711, 2015). "In addition, both univariate and multivariate logistic regression analyses showed that tubular atrophy/interstitial fibrosis, interstitial inflammation, arteriosclerosis, and arteriolar hyalinosis were significantly associated with the semi-quantitative percentage of CD4 immunostaining." (PMID 39654881, 2024). "Within this milieu of IL-1α- and IL-1-induced cytokines CD4 memory T cells will be pushed toward the Th17 lineage with production of IL-17 and instigate arteriosclerosis and graft rejection." (PMID 26324711, 2015). "CD4 T cells comprise a variety of cell types that can produce variable cytokines with both positive (e.g., angiogenesis) and negative (e.g., arteriosclerosis) effects on vascular function." (PMID 34220551, 2021).
Arthralgia (6 papers, 2013 to 2025). "Whereas absolute numbers of CD4+CD161+ T-cells were found increased in the seropositive arthralgia group, a profound decrease of these cells was found to mark the early RA state." (PMID 24223933, 2013). "Within the CD4 T cell pool, the frequency and absolute numbers of circulating naïve T cells were lower in arthralgia patients (p = 0.031), undifferentiated arthritis (p = 0.0023) and were maintained in those with diagnosed RA of more or less than 3 months symptom duration (both “p < 0.0001”)." (PMID 40908179, 2025). "Similar pathogenic effects of virus-specific CD4+ T cells were previously reported for other alphaviruses, including CHIKV, and Sindbis virus (SINV), suggesting that targeting CD4+ T cells is a viable treatment option for patients suffering of ONNV-induced arthralgia." (PMID 32477364, 2020). "We have observed a significant increase in frequency of EMRA CD4 T cells and regulatory T cells in ACPA+ve patients with arthralgia irrespective of whether they developed RA or not, p = 0.041 and p = 0.032 respectively compared to ACPA−ve arthralgia patients." (PMID 40908179, 2025).
atrophic gastritis (6 papers, 2018 to 2025). "In extensive atrophic gastritis, the expression of CCL2 and CCL19 was correlated with the infiltration of central memory CD4 T cell, and CD56dim natural killer cell was associated with IL33 expression." (PMID 33426088, 2020). "Thus, the usefulness of antrum CD8+/CD4+ should be investigated in a population including patients with gastric atrophy of unknown etiology." (PMID 35735608, 2022). "In an atrophic gastritis environment, the expression of CXCL14, CCL4, CCL26, CCL21, CCL2, CCL19, and CCL13 was correlated with the infiltration of central memory CD4 T cell." (PMID 33426088, 2020). "In normal gastric mucosa, superficial gastritis, atrophic gastritis, and extensive atrophic gastritis with/without intestinal metaplasia, the most infiltrating immune cells were all central memory CD4 T cells and monocytes." (PMID 33426088, 2020).
B-cell acute lymphoblastic leukemia (6 papers, 2014 to 2025). A neoplasm of lymphoblasts committed to the B-cell lineage, typically composed of small to medium-sized blast cells. "However, activin A also contributes to the switching of CD4+CD25-Foxp3- (Foxp3: forkhead box P3) cells to CD4+CD25+Foxp3+ T-regulatory (Treg) cells, which correlates with immunosuppression in patients with B-cell acute lymphoblastic leukemia." (PMID 25560921, 2014). "Both CD8+ and CD4+ donor T cells from Itk-/- mice produce less inflammatory cytokines and show decrease migration to GVHD target organs such as the liver and small intestine, while maintaining GVL efficacy against primary B-cell acute lymphoblastic leukemia (B-ALL)." (PMID 33324410, 2020).
biliary atresia (6 papers, 2012 to 2024). A rare, biliary tract disease characterized by progressive obliterative cholangiopathy of the intra- and extrahepatic bile ducts, occurring in the embryonic/ perinatal period, leading to severe and persistent neonatal jaundice and acholic stool. "Our previous results indicated that the genomic DNA of CD4+ T lymphocytes in the peripheral blood of children with biliary atresia was generally hypomethylated and that the expression of DNA methyltransferase (DNMT) 1 was significantly decreased." (PMID 29748604, 2018). "Some studies have shown that biliary atresia is a type of CD4+ helper T-lymphocyte 1 (Th1)-mediated autoimmune diseases." (PMID 29748604, 2018). "In addition, immune correlation analysis revealed that SPP1 expression was higher in resting CD4 memory T cells and lower in regulatory T cells in the diagnosis of biliary atresia, suggesting that SPP1 mediated CD4+ T-cell and regulatory T-cell infiltration." (PMID 38919629, 2024).
bone marrow failure (6 papers, 2018 to 2025). "CD4+ Th1 cells play a significant role in the pathogenesis of bone marrow failure by secreting pro-inflammatory cytokines like IFN-γ and TNF-α, which mediate HSPC apoptosis." (PMID 40552264, 2025). "It is likely that similar to what is observed in HIV patients, high levels of inflammation, bone marrow failure, reduced thymic output, and splenic sequestration contribute to the lower CD4+ T cells counts in VL patients." (PMID 35106507, 2022). "Our results indicated that Coptidis alkaloid treatment could interfere with the differentiation of CD4+ T cells, deplete the expansion of Th1 and Th17 cells, augment the proportions of Th2 and Treg cells, and reduce the severity of bone marrow failure mediated by immune destruction." (PMID 32706801, 2020). "In addition to bone marrow failure, reduced thymic output may play a role in the lower number of CD4+ T cells, and indeed, a recent study showed a clear correlation between decreased numbers of recent thymic emigrants and poor CD4+ T cell recovery in HIV patients." (PMID 35106507, 2022). "Epimedium polysaccharide improves T cell immune mediation by increasing the number of CD3+ and CD4+ cells and the ratio of CD4+/CD8+, thereby enhancing immune function and reducing hematologic toxicity in mice with benzene-induced bone marrow failure." (PMID 35804765, 2022). "In summary, platelets regulate the immune responses of CD4+ and CD8+ T cells through mitochondrial energy metabolism, contributing to immune dysregulation and increased levels of IFNγ and TNFα, leading to the destruction of HSPCs and potential bone marrow failure." (PMID 40552264, 2025).
bovine tuberculosis (6 papers, 2011 to 2024). "We have previously used this package to prioritize CD4+ epitopes in the proteome of M. bovis (Mycobacterium tuberculosis variant bovis AF2122/97) for potential use in novel antigens for bovine tuberculosis." (PMID 36824339, 2021). "For instance, calves typically infected with bovine tuberculosis had a predominance of TNF-α+IFN-γ+IL-2+ and TNF-α+IFN-γ+IL-2− CD4+ T cells with a TEM phenotype." (PMID 36960295, 2023). "However, this characterization of the CD4+ T cell subsets and kinetics of the memory response induced by BCG vaccination in cattle will contribute to development of a more efficacious vaccine for bovine tuberculosis." (PMID 39664903, 2024).
bullous pemphigoid (6 papers, 2013 to 2025). Bullous pemphigoid (BP) is the most common form of autoimmune bullous dermatosis. "CD62L has been reported to be associated with CD4+CD25brightFOXP3+ cells in bullous pemphigoid patients." (PMID 24039568, 2013). "Our review identified keratinocytes as crucial mediators in bullous pemphigoid, predominantly orchestrating Th2-driven inflammation through secretion of cytokines including IL-16, leading to CD4+ T cells recruitment and amplification of the IL-4/IL-13 axis." (PMID 41479908, 2025).
Candidemia (6 papers, 2012 to 2022). A form of invasive candidiasis where species of CANDIDA are present in the blood. "Among 267 participants in whom CD4 count was recorded near the date of the candidemia diagnosis, the median CD4 count was 133 (IQR 42–309) cells/μL; 166/267 (63%) had a CD4 count <200 cells/μL." (PMID 34014153, 2021). "Compared to control patients, the MFI for PD-L1 was increased in CD4 T cells from patients with Candidemia; p <0.05." (PMID 26786705, 2016). "Compared to control patients, CD8 T cells from patients with Candidemia had evidence of cellular activation as indicated by increased CD69 expression while CD4 T cells had decreased expression of the major positive co-stimulatory molecule CD28." (PMID 26786705, 2016). "Despite a large proportion having received previous antiretroviral treatment, the median CD4 count among hospitalized HIV-seropositive participants with candidemia in this study was 133 cells/μL, and almost two thirds had advanced HIV disease (defined by the WHO as a CD4 count of <200 cells/μL)." (PMID 34014153, 2021). "The expression of PD-1 and PDL-1 on CD4+ and CD8+ T lymphocytes in patients with candidemia leads to lymphocyte exhaustion." (PMID 36010061, 2022). "Although the difference did not quite reach statistical significance, there was a trend toward a decreased percentage of CD4 T cells positive for the IL-7R and decreased MFI in patients with Candidemia compared to controls, p = 0.08 and p = 0.07 respectively." (PMID 26786705, 2016). "CD4 and CD8 T cells from patients with Candidemia expressed markers typical of T cell exhaustion as indicated by either increased percentages of or increased MFI for programmed cell death 1 (PD-1) or its ligand (PD-L1)." (PMID 26786705, 2016). "In contrast to the increase in inhibitory receptor/ligands noted in CD8 T cells, there was a significant decrease in the percentage of CD4 T cells expressing CD28, a major positive co-stimulatory molecule, in patients with Candidemia compared to controls, 79.8 % versus 92.6 %, respectively; p <0.05." (PMID 26786705, 2016).
cholera (6 papers, 2018 to 2023). "HIV self-testing, CD4 count, Crypotococcal antigen and cholera diagnostic tests were largely left out from all national recommendations, except for Nigeria." (PMID 37200237, 2023). "It was suggested that the failure of the current oral cholera vaccines to activate CD4+ responses might be linked to the short duration of protection." (PMID 34201310, 2021). "It has been demonstrated that the initial CD4+ T-cell responses to V. cholerae infection or antigens have an important role in the induction of long-term protection against cholera through the development of long-lived memory B cells." (PMID 34732259, 2021). "We show microbiome-specific effects on host antibody responses against Vibrio cholerae, and that dysbiotic human gut microbiomes representative of cholera-endemic areas suppress the immune response against V. cholerae via CD4+ lymphocytes." (PMID 34877500, 2021). "In light of these findings, a thorough assessment of CD4+ T cells and B cell population involved in maintaining long-term immunity to cholera after “LPS + LPS‐MSC‐CM” vaccine under controlled clinical settings seems warranted." (PMID 34732259, 2021). "While IL-13 levels have been assessed, these studies are generally done in investigations of CD4+ cell responses to cholera." (PMID 34888255, 2021). "It has also been revealed that due to the presence of CtxB in the whole cell vaccine formulation, the most CD4+ T cells responses skewed to regulatory T cells (Tregs) compared to the TH1 and TH17 related to short-term immunity to cholera." (PMID 34732259, 2021). "Our current understanding of CD4+ T cell responses is lacking, as is knowledge of the downstream cytokines and effector functions produced by these cells during cholera." (PMID 34888255, 2021).
chronic asthma (6 papers, 2014 to 2024). An asthma that is characterized by the development of persistent airway inflammation and recurrent attacks of breathlessness and wheezing, which vary in severity and frequency. "Further support for the presence of a mixtured Th phenotype in pathological situations is provided by a study on patients with chronic asthma, where CD4+T-cell clones with a Th17/Th2 phenotype that also produced IL-22 were identified." (PMID 30893757, 2019). "Our results suggest that in the airways of chronic asthma patients there is an imbalance between increased numbers of CD4+IL-17+ cells and Th2 cells and decreased number of CD4+Foxp3+TGF-β+." (PMID 25132806, 2014). "This study indicated that the administration of MJZT during a phase of remission could suppress airway inflammation by inhibiting Teff cells (Foxp3-CD25+CD4+) in a mouse model of chronic asthma." (PMID 30873032, 2019). "We found that in BAL fluid of patients with chronic asthma have a decreased population of CD4+Foxp3+TGF-β+ cells and at the same time an increased population of CD4+IL-17+ cells, CD4+IL-17+ IFN-γ+ cells and CD4+IL-4+ cells." (PMID 25132806, 2014). "In conclusion, our results suggest that in the airways of chronic asthma patients there is an imbalance between the increased population of CD4+IL-17+ cells, CD4+IL-17+IFN-γ+ cells and CD4+IL-4+ cells and the decreased population of CD4+Foxp3+TGF-β+ cells." (PMID 25132806, 2014). "However, in an animal model of acute exacerbation M2 macrophages triggered Th2 cytokines in CD4+ T-lymphocytes through the interaction with CD80/CD86, which was not seen in a model of mild chronic asthma." (PMID 24612750, 2014).
coagulopathy (6 papers, 2011 to 2024). "When infected with simian immunodeficiency virus (SIV), pigtail macaques (PTM) exhibit rapid and severe disease relative to RhM and CyM, including rapid destruction of the CD4 immune compartment, severe gastrointestinal disease, and complications related to coagulopathy." (PMID 34929014, 2021). "With dramatical decrease of CD4+ T cells and CD8+ T cells, extraordinarily increased neutrophils and severe inflammatory responses are involved in ARDS, MODS, and coagulation disorders and can even lead to DIC and death in severe cases." (PMID 32983157, 2020).
cysticercosis (6 papers, 2014 to 2025). "In murine (BALB/c) cysticercosis caused by T. crassiceps, macrophages and T CD4+ cells are the major players that modulate the Th1/Th2 balance and the parasite growth." (PMID 30538171, 2019). "However, when the CD4 count × cysticercosis status interaction term was removed, the association slightly changed but remained significant (β = –0.0007, 95% CI: –0.0013 to –0.0001, p = 0.004)." (PMID 40046043, 2025). "Multivariate regression analysis of cytokine levels in relation to CD4 count, cysticercosis status, and other confounding factors." (PMID 40046043, 2025). "Cysticercosis-positive individuals showed positive correlations between CD4 counts and pro-inflammatory cytokines (e.g., TNF-α, IL-1β), contrasting with negative correlations in cysticercosis-negative individuals." (PMID 40046043, 2025). "This aligns with a previous study in Mozambique reporting lower cysticercosis antibody rates in patients with lower CD4 counts." (PMID 41003557, 2025). "MANOVA results for cytokine levels across CD4 categories and cysticercosis status." (PMID 40046043, 2025). "A nested study within a cross-sectional analysis in two Tanzanian regions was performed and 234 participants (110 HIV+ and 124 HIV-) were tested for cysticercosis antibodies, antigens, CD4 counts and serum Th1 and Th2 cytokines via multiplex bead-based immunoassay." (PMID 39093864, 2024). "After adjusting for CD4 count and HIV clinical stage, patients positive on cysticercosis Western Blot IgG had four times higher odds of harboring cysts in the brain compared with Western Blot-negative peers." (PMID 41003557, 2025). "However, overall cytokine profiles were not significantly influenced by CD4 categories or cysticercosis status." (PMID 40046043, 2025). "For IFN-γ, the association with CD4 count remained significant across most exclusions (β = –0.0010, 95% CI: –0.0018 to –0.0002, p = 0.021) but became non-significant when excluding the CD4 count × cysticercosis status interaction term (β = –0.0006, 95% CI: –0.0012 to 0.0000, p = 0.088)." (PMID 40046043, 2025). "In cysticercosis, Tregs induction seems to participate in the control of the inflammatory responses since a negative correlation between the percentage of peripheral Tregs and activated CD8+ and CD4+ T cells, along with a depressed T-cell proliferative response has been observed." (PMID 31694049, 2019).